RN7SKP57 (RN7SK pseudogene 57)
Gene: Miscellaneous RNA gene on chromosome 5 (111,719,769 to 111,720,061, reverse strand). Ensembl gene ENSG00000253057.
Homologues: Orthologues: chimpanzee 7SK (99% identical), guinea pig RN7SKP57 (55% identical). Paralogues in human: RN7SKP187 (58% identical), 7SK (57% identical), RN7SKP76 (56% identical), RN7SKP178 (56% identical), RN7SKP174 (55% identical), RN7SKP48 (55% identical), RN7SKP86 (55% identical), RN7SKP104 (55% identical), RN7SKP180 (55% identical), RN7SKP245 (55% identical), RN7SKP160 (55% identical), RN7SKP294 (55% identical), and 283 more.